MIR6731 (microRNA 6731)
Synonyms: hsa-mir-6731
Gene: MicroRNA gene on chromosome 1 (24,919,345 to 24,919,416, reverse strand). Ensembl gene ENSG00000278034.
Homologues: Orthologues: chimpanzee MIR6731 (100% identical).